GNAS (GNAS complex locus)
Diseases named in the same sentence as GNAS in open-access papers (continued):
Sharing a sentence is not in itself a finding about the gene and the disease.
cancer (167 papers, 2003 to 2026). A tumor composed of atypical neoplastic, often pleomorphic cells that invade other tissues. "GNAS, which frequently acquires activating mutations in cancer, encodes the G-protein Gα subunit that participates in G-protein signaling and activates downstream signaling pathways, including direct interactions with MAPK signaling." (PMID 40414875, 2025). "In in vitro functional validation revealed that engineered T cells therapies eliminated 80% of cancer cells carrying GNAS splice variants within 72 hours, establishing a mechanistic for pan-cancer vaccine development." (PMID 40661781, 2025). "GNAS mutations occur in a variety of cancers, when GNAS is activated, the cAMP pathway becomes linked to the RAS-RAF-MEK-ERK signaling pathway, cell proliferation and angiogenesis in appendiceal cancers." (PMID 39928247, 2025). "Pathogenic variants in codon 201 or codon 227 of GNAS were assessed using direct cycle Sanger sequencing and Ion AmpliSeq Cancer Hotspot Panel v2 methodologies." (PMID 38317844, 2024). "GNAS mutations have been associated with abnormal mucinous secretion and an alternative mechanism of Wnt/β-catenin signaling activation in different cancer types." (PMID 39018564, 2024). "In recent years, activating mutations in the Gαs-encoding gene GNAS have been detected in multiple cancer types, such as pancreatic and colorectal cancers." (PMID 39242543, 2024). "A diagnostic tool to distinguish 10 cancers by two or more positive genes of gene classes (GNAS, GRB10, and SNRPN)." (PMID 38812777, 2024). "Pathogenic variants in codon 201 of the GNAS gene on chromosome 20 are one of the primary cancer-causing variants in heterotrimeric G proteins and is one of the leading causes of oncogenesis in a variety of low-grade malignant and benign tumors." (PMID 38317844, 2024). "We found that a small number of genes (e.g., RET, RECQL4, CUX1, FGFR4, PIK3R1, FGFR3, and GNAS) had some co-occurring variants per patient in different cancer types." (PMID 38637555, 2024). "Given the recent advances in clinical trials to directly target KRAS and GNAS mutations in other cancers, we propose a rationale to explore these mutations in future pre-clinical studies in PMP with a view for a future clinical trial." (PMID 36723696, 2023). "Both LGASC and its associated MSC harbored the common GNAS c.C2530T:p.Arg844Cys mutation, which was more frequently detected in the cancer cell fraction of MSC." (PMID 37650999, 2023). "GNAS is one of the most frequently mutated genes in human cancer and its mutations are widespread in various malignancies." (PMID 38107305, 2023). "Even though DNAJB1-PRKACA in FL-HCC clearly shows that PKA is an oncogenic driver, a larger analysis of cancer genomes showed that guanine nucleotide-binding protein alpha stimulating (GNAS) is the most frequently mutated G protein." (PMID 35805104, 2022). "GNAS gene mutation is a comprehensively investigated mutation in many cancers probably because it functions as the most common cancer-initiating mutation across the heterotrimeric G-proteins, the Gα-subunit cascade of the MAPK/ERK pathway." (PMID 36428574, 2022). "Surprisingly, another study shows that GNAS-mutated cancers are more likely to be gastrointestinal cancers, such as colorectal adenocarcinoma (4–10%), stomach adenocarcinoma (6–10%), and pancreatic adenocarcinoma (5–12%)." (PMID 35805104, 2022). "Subsequent studies characterizing these concomitant carcinomas highlighted an association with branch-duct and gastric type IPMNs and the lower prevalence of GNAS mutations." (PMID 34201897, 2021). "Activation of cAMP signalling via means other than by activating GNAS mutations suggests both an explanation for off-label drugs with potential actions against cancer, and the means to identify additional cancer targeting drugs." (PMID 31337866, 2019).
cancer (continued). "Because three GNAS mutant tumors were also MSI tumors, it is possible that including MSI cancers skews the association of GNAS mutations with the proximal colon." (PMID 24498230, 2014). "Finally, additional trials to follow on successful initial results are required in the case of appendiceal carcinomas with GNAS mutations and to further elucidate the mechanisms of sensitivity or resistance of these cancers to CDK4/6 inhibitors." (PMID 40699853, 2025). "The gold standard for sensitive screening for genes that can predispose a patient to particular cancer types, such as pathogenic variants in GNAS, was PCR amplification, followed by sequencing, e.g., Sanger sequencing (also known as dideoxy chain termination method) of the amplified product." (PMID 38317844, 2024). "GNAS is considered to be an oncogene that can be constitutionally activated by a specific point mutation of Guanine nucleotide binding protein alpha subunit (Gsα) in the Estrogen signaling pathway, thus activating multiple cancer-related pathways." (PMID 38280998, 2024). "Given the recent advances in clinical trials to directly target KRAS and GNAS mutations in other cancers, we propose a rationale to explore targeting KRAS G12C and G12D, and GNAS R201H and R201C in pre-clinical studies in PMP to produce preliminary results supporting a future clinical trial." (PMID 36723696, 2023). "Methylation of RASSF1A, CDKN2A, and LINE-1 and GNAS mutation may be relevant to cancer development, IPMN subtypes, and cancer prognosis." (PMID 35013462, 2022). "GNAS, as one of the most common mutated genes, has been shown to be closely related to cancers." (PMID 35052777, 2022). "Finally, DD1522 displayed a deletion in the MAP2K1 gene, which is affected in a high number of cancers and a previously reported hot spot mutation in GNAS (R201H)." (PMID 35954444, 2022). "GNAS gene mutations has been altered in 3.21% of all cancers." (PMID 36428574, 2022). "Furthermore, targeted sequencing with cancer‐related genes revealed the relationships between the altered gene and metastatic sites, age, gender, smoking, etc.,16, 17 and alterations in GNAS and RB1 were reported to be associated with disease recurrence." (PMID 33455072, 2021). "The majority of GNAS mutations detected in our analysis were classified as amplifications in 10 patients, and two patients had mutations in R201C and R201H, which have been connected with cancer progression in the past." (PMID 35141142, 2021). "Indeed, 71% of TCGA cancer types characterized by GNAS activating mutations also show overall higher activity of the Gs pathway, which is the most activated in 75% of the considered cancer types." (PMID 31337866, 2019). "GNAS mutations are frequently involved in IM, in contrast to these other malignant tumors." (PMID 30736805, 2019). "In addition to oncogenic activation of GNAS, a variety of cancer-associated alterations can enhance GPCR-GNAS-PKA signaling, including activating mutations in the catalytic subunit of PKA, inactivating mutations in the regulatory subunit of PKA, and overexpression of cAMP-stimulating GPCRs70–73." (PMID 37714844, 2023). "In this study, we investigated the germline mutation alterations of ADAM6, SIX3, GNAS, NDUFV1, H19, DEFA4, and ZIM2 genes in 82 pediatric cancer patients treated with cisplatin." (PMID 41009448, 2025). "In cancer cells, the expression of four SRGs (PI3, AUP1, CD200 and GNAS) is closely associated with epigenetic regulation and epithelial-mesenchymal signaling." (PMID 40534859, 2025).
cancer (continued). "Through integrative analysis of > 5000 samples spanning 12 cancer types, researchers identified recurrent splicing errors in genes such as GNAS and RPL22 that exhibit cross-tumor stability and are effectively recognized by adaptive immunity." (PMID 40661781, 2025). "On the other hand, DE of heterotrimeric G-protein α subunits showed that GNAS was the single most widely upregulated subunit, being significantly over-expressed in 94% of cancer tissues, confirming previous analyses." (PMID 38723607, 2024). "Among the top three candidates for both gains and losses, CDKN2C gain, KIT loss, and GNAS loss were unique to GC cell lines, while ERBB3 gain, FBXW gain, and hypoxia-inducible factor 1a loss were also observed in other cancer types." (PMID 39461475, 2024). "We chose CRC cells, as deregulation of the GNAS-cAMP-PKA signaling axis is particularly common in this type of cancer." (PMID 38568213, 2024). "A pan-cancer cohort of patients from 1050 GNAS mutant tumors showed a heavy disposition to the p.R201 codon, with a classic gain-of-function mutation." (PMID 38317844, 2024). "Of these genes, GNAQ, GNAS, and JAK2 are associated with cell growth-related factors, whereas NRAS, IDH2, and CTNNB1 are cancer-related genes." (PMID 36780540, 2023). "GNAS codon 201 aberrations are particularly frequently detected in cancer, especially as they lead to fundamental activation of Gsα and autonomous cyclic-AMP release." (PMID 36428574, 2022). "We illustrated an example of MC profile alteration in the promoter of GNAS, which LoI has been described in diverse types of cancer." (PMID 36601577, 2022). "Most studies on GNAS in cancers were performed at the gene level, and a few studies on GNAS were carried out at the protein level; however, none of them, except our recent study, are related to GNAS autoantibody in sera from patients with HCC." (PMID 35052777, 2022). "We found a rather narrow range of other genes (KMT2D, FBXW7, GNAS, ARID1A, NF1 and CTNNB1) harbouring mutations in 6–12% of the patients and a long tail of cancer genes with mutations in <6%." (PMID 34647903, 2021). "For this investigation, we focused on the expression status of three imprinted genes—GNAS, GRB10, and SNRPN known to be associated with cancer status." (PMID 32448196, 2020). "We therefore selected GNAS, GRB10, and SNRPN genes as the more efficient cancer biomarkers for our diagnostic model." (PMID 32448196, 2020). "To analyze the allelic expression of imprinted genes in cancer, we selected 5 imprinted genes GNAS, GRB10, SNRPN, IGF2, and IGF2R which were mostly reported to be associated with cancer." (PMID 32448196, 2020). "The much greater expression of GNAS relative to the other G protein genes in all cancers, would also imply that Gs signalling is prevailing (i.e., even in the absence of any GNAS activation) and hence needs to be strictly controlled." (PMID 31337866, 2019). "For example, in cancer, GNAS, BCR and SNRPN showed both expression downregulation and CNV losses, while for HM13, gains were linked with overexpression." (PMID 30297886, 2018).
cancer (continued). "For example, the four imprinted regions on chromosome 20q (MCTS2, NNAT, L3MTBL1 and GNAS) were invariable subject to copy-number gains with very few deletions observed in the four cancer types." (PMID 28883545, 2017). "In patient 1, mutations in ATM and GNAS, as well as a deletion in the tumor suppressor gene PTEN, likely led to tumorigenesis since they are potential cancer driver genes." (PMID 29169336, 2017). "Next, we analyzed 274 mutations in 24 cancer-relevant genes (Sequenom technology), including BRAF, NRAS, KIT c-MET, GNAS and GNAQ." (PMID 27057633, 2016). "First, we targeted the following loci given the initial observation from TCGA: five imprinted domains (PEG3, H19/IGF2, DLK1/GTL2, MEST, GNAS) and four cancer genes (APC, MLL3, MGMT, ELF3)." (PMID 26338779, 2015). "In cases with wild-type KRAS, BRAF and PIK3CA a number of cancer-associated genes representing potential drivers were identified (for example, STK11, GNAS, CHEK2 and RB1)." (PMID 25855536, 2015). "Among the 46 cancer-related genes, KRAS and GNAS mutations were most frequently detected in both PDAC and IPMN cases." (PMID 24897499, 2014). "GNAS (G protein alpha subunit) functions as a crucial transduction protein capable of activating the Wnt/β-catenin and Hedgehog signaling pathways, thereby influencing the onset and progression of cancer." (PMID 39484038, 2024). "We found that GNAS is widespread over-expressed across cancer, which might be connected to its critical role in controlling cell energetics and metabolism via cyclic AMP (cAMP) and PKA signaling, ultimately sustaining tumorigenesis and resistance mechanisms." (PMID 38723607, 2024). "GNAS, as a common oncogene, is involved in the pathogenesis of various cancers." (PMID 38107305, 2023). "In addition, we also detected multiple PUD risk, cancer-related genes (for example, IHH, GNAS, NHEJ1, JUP and MECOM), which provided potential targets contributing to the different outcomes of PUD or GC." (PMID 38036781, 2023). "Several of the cancer-related genes we identified, including PIK3CA, KRAS, GNAS, and PPM1D, could also have haematological mutations." (PMID 37175518, 2023). "We thus hypothesized that activation of GNAS could be a general strategy employed by human cancers to inhibit T cell infiltration." (PMID 37714844, 2023). "The GNAS gene is included as a tier 1 proto-oncogene in the cancer gene census (CGC) database." (PMID 36151521, 2022). "During the process of tumorigenesis, GNAS changes in quantity and quality, which may trigger an immune response leading to autoantibody production in cancer patients." (PMID 35052777, 2022). "Until now, numerous reports have described the relationship between GNAS genotype and cancer, showing that the TT/TC genotypes exert a protective effect against cancer progression, with improved overall patient survival rates in a variety of cancer entities." (PMID 36297195, 2022). "Genetic mutations have been shown to be hugely important in the study of many cancers and pancreatic cancer is no different, with GNAS and KRAS mutations representing the predominant mutations observed in this cancer." (PMID 33673153, 2021).
cancer (continued). "GNAS and GNAQ encode G-protein alpha subunit, and the viruses like cytomegalovirus and EBV have been identified to encode G proteins and their coupled receptors in their genomes to induce cancer initiation." (PMID 34926267, 2021). "While analyzing multiple cancer disorders, we found highly variable expression among genes implicated in cancer: EEF1A1, GNAS, NPM1, PIM1, and RHOA are known oncogenes; H3F3A, PTPRC, SMARCB1, and B2M are possible oncogenes; and CASP8, JAK1, and PRKAR1A are known tumor suppressor genes." (PMID 34174938, 2021). "In order to find useful and efficient cancer biomarkers for clinical applications, we generated the ROC curves for the GNAS, GRB10, SNRPN, IGF2, and IGF2R imprinted genes using the individual BAE, MAE, and TE measurements for all the different cancer types combined." (PMID 32448196, 2020). "Nonsynonymous mutations in four cancer-associated genes, CTNNA2 (11.1% vs. 5.8%; log10 p-value = −0.6), FLG (8.9% vs. 4.3%; log10 p-value = −0.6), GNAS (4.4% vs. 1.4%; log10 p-value = −0.5), and BCORL1 (17.0% vs. 11.6%; log10 p-value = −0.5), were more abundant in the case group." (PMID 32566745, 2020). "In addition, we found DAMEs corresponding to known regions exhibiting loss of imprinting in cancer, including those in the genes MEG3, H19, and GNAS." (PMID 32487212, 2020). "In 17 of the 18 cases, at least one somatic mutation in the initiating driver genes KRAS and GNAS was shared between the noninvasive component and associated invasive cancer, with the remaining case lacking mutations in these genes." (PMID 32796935, 2020). "By integrating transcriptomics and interaction data, we show that the Gs pathway is upregulated in multiple cancer types, even those lacking known GNAS activating mutations." (PMID 31337866, 2019). "Cases negative for a GNAS mutation can be considered to have an increased risk of invasive cancer derived from an IPMN." (PMID 31799082, 2019). "Other mutations among a panel of 39 cancer-related genes do not further add to performance over GNAS and KRAS." (PMID 27992432, 2016). "When examined for anatomical location within the colon, all ten GNAS mutant samples were found to be derived from primary cancers that originated in the proximal colon, between the cecum and splenic flexure, lesions commonly referred to as right-sided (P<0.007, Fisher's exact test)." (PMID 24498230, 2014). "Somatic GNAS mutations have been detected in a range of human cancers and in fibrous dysplasia, a disorder of bone development that does not appear to progress to cancer." (PMID 36313756, 2022). "Moreover, elevated GNAS expression can enhance cancer cell migration." (PMID 36151521, 2022). "In addition, extensive EFEMP1 methylation was particularly present in malignant tumors without GNAS mutations and associated with disease-free survival of patients with IPMNs (p < 0.0001)." (PMID 27095449, 2016). "The carcinoma population had a very high TFx (0.96), with 34 sCNA and regions containing FGFR1, CCND1, GNAS, and BRAF the most amplified." (PMID 41144934, 2026). "All three carcinoma populations of different DI showed similar profiles with sCNA, including MYC, GNAS, BRAF amplifications and, as expected, ERBB2 high‐level amplification." (PMID 41144934, 2026). "Within the TCGA HGSOC cohort, GNAS expression was significantly correlated with expression of the EMT markers Vimentin and N-cadherin, and the cancer cell stemness marker PROM1." (PMID 38097740, 2024). "By cross-referencing these sources, we identified five top oncogenes—ALK, EGFR, GNAS, KRAS, and PIK3CA —due to their frequent occurrence and their critical roles in multiple cancers." (PMID 39684787, 2024).